BDNF (brain derived neurotrophic factor)
Diseases named in the same sentence as BDNF in open-access papers (continued):
Sharing a sentence is not in itself a finding about the gene and the disease.
colon cancer (23 papers, 2011 to 2025). "The combination of CD66b, BDNF, and CysLT1R was shown to be useful for detecting high-risk colon cancer patients." (PMID 34771682, 2021). "These public colon cancer datasets showed a statistically significant association between BDNF and two neutrophilic markers, CD66b and neutrophil elastase (ELANE)." (PMID 34771682, 2021). "An investigation of a cohort of human colorectal tissues (tumor n=66; normal n=88) using quantitative PCR and immunohistochemistry demonstrated that BDNF is aberrantly expressed in human colon cancer and a significantly raised level of BDNF is associated with its stage at diagnosis." (PMID 24255678, 2013). "It is concluded that BDNF, a neurotrophic growth factor aberrantly expressed in cancers such as colon cancer, has a profound impact on the cellular behavior of colon cancer cells and that BDNF is associated with a reduction in the apoptosis of colon cancer." (PMID 24255678, 2013). "Another study was involved that the presence of human BDNF significantly increases the metastatic potential of colon cancer cells." (PMID 37460933, 2023). "In colon cancer, knockdown of the neurotrophic factor BDNF suppresses the expression of the mesenchymal marker CDH2 leading to anoikis and immune resistance in tumor cells." (PMID 36291283, 2022). "In the colon cancer group, the serum BDNF concentrations significantly fell postoperatively in the entire group (p = 0.0076) and in subgroups of patients with or without resections (p = 0.034, p = 0.0179, respectively)." (PMID 34395067, 2021). "We determined serum BDNF concentrations in patients with pancreatic or colon cancer, before and after surgery." (PMID 34395067, 2021). "qRT–PCR assays showed that the mRNA expression levels of TIMP1 and BDNF were significantly higher in colon cancer cells than in NCM460 cells." (PMID 35003085, 2021). "In this study, we found that high levels of neutrophils (CD66b) and brain-derived neurotropic factor (BDNF) goes with poor prognosis for colon cancer patient." (PMID 34771682, 2021). "For instance, in colon cancer, BDNF exerts its cancer-promoting function by facilitating HO-1 expression and VEGF transcription, accompanied by the activation of MAPK signaling pathway." (PMID 33942699, 2021). "Human BDNF enhanced the migratory activities of colon cancer cell lines SW480 and HCT116, through modulating VEGF/HO-1 activation via the ERK, p38, and PI3K/Akt signaling pathways." (PMID 35003085, 2021). "In summary, to the best of our knowledge, the current study presents for the first time a positive correlation between BDNF and CysLT1R in colon cancer patients." (PMID 34771682, 2021). "BDNF/TrkB signaling participates in the formation of drug resistance in HT-29 colon cancer cells through an EGFR-dependent mechanism." (PMID 35003085, 2021). "BDNF one of the most interesting genes for further studies, especially regarding its biological implications for colon cancer migration and CICs." (PMID 32971738, 2020). "Expression of BDNF also occurs in cancers such as colon cancer, and alters the behavior of cancer cells at cellular level." (PMID 27875990, 2016). "On EE housing, mice with subcutaneous implanted melanoma or colon cancer had reduced tumour development and progression, with mechanisms involving hypothalamic BDNF and sympathetic modulation." (PMID 25818172, 2015). "The present study aimed to investigate the biological roles of BDNF expression in human colon cancer." (PMID 24255678, 2013). "In conclusion, our study shows that BDNF facilitates cell proliferation and inhibits cell apoptosis in human colon cancer cells." (PMID 24255678, 2013). "A set of anti-BDNF ribozymes were used to transfect colon cancer cells in order to generate BDNF knockdown cells to evaluate the effect on growth and apoptosis." (PMID 24255678, 2013).
colon cancer (continued). "We observed high expression of BDNF in Caco-2, HRT18 and RKO human colon cancer cells and therefore anti-BDNF ribozymes were constructed to knock down the expression of BDNF in these cell lines." (PMID 24255678, 2013). "The present study aimed to investigate the effect of modulation of BDNF at the transcription level on the cellular function of colorectal cells and to increase our understanding of its biological role in human colon cancer." (PMID 24255678, 2013). "In the present study we obtained stable knockdowns of BDNF in human colon cancer cell lines using anti-BDNF ribozymes." (PMID 24255678, 2013). "BDNF is therefore a potential therapeutic target in colon cancer and its effect in human colon cancer requires further investigation." (PMID 24255678, 2013). "Nonetheless, exposure to BDNF of both rat epithelial and human colon cancer cells expressing these mutants resulted in reduced receptor activation of TRKBT695I and almost no activation of TRKBD751N." (PMID 21379385, 2011). "Our results indicate that high tumor-infiltrating neutrophils in patients with colon cancer is associated with poor prognosis and that the tumor associated neutrophils (TAN) can be the source of BDNF production in the TME, where BDNF can further accelerate tumor progression." (PMID 34771682, 2021). "Furthermore, our IHC analysis of the CC cohort showed that high BDNF expression was significantly upregulated in colon cancer tissues, which was correlated with poor survival." (PMID 34771682, 2021). "We next explored the relation between BDNF, neutrophils, and CysLT1R in colon cancer tissue." (PMID 34771682, 2021). "Additionally, BDNF promoted the proliferation of human colon cancer cells, and its levels were significantly elevated in tumours with poor prognosis." (PMID 35003085, 2021). "BDNF is a key mediator of the hypothalamus-adipocyte axis, with studies indicating that this neuroendocrine axis shows antiobesity and anticancer functions in animal models of melanoma and colon cancer." (PMID 33574842, 2021). "By TrkB/ERK1/2 pathway, BDNF could promote colon cancer cells and human microvascular endothelial cells migration." (PMID 32803867, 2020). "Finally, in human colon cancer cells, cetuximab reduces the expression of both BDNF and TrkB, and this effect can be attenuated by the addition of recombinant BDNF." (PMID 29581842, 2018). "Significant reduction of growth, incidence and proliferation of subcutaneous implanted melanoma and colon cancer is reported on EE housing, with involvement of hypothalamic brain-derived growth factor (BDNF), sympathetic innervation of white fat and inhibition of leptin levels." (PMID 25818172, 2015). "The expression profile of BDNF in human colon cancer cell lines was evaluated using RT-PCR." (PMID 24255678, 2013). "BDNF gene transcripts were successfully detected in the colon cancer cell lines, Caco-2 and HRT18." (PMID 24255678, 2013). "Our results also show that the mRNA expression level of BDNF in human colon cancer is elevated." (PMID 24255678, 2013). "We conclude that BDNF is able to maintain colon cancer cell survival and proliferation." (PMID 24255678, 2013). "Brain-derived neurotrophic factor (BDNF), induced by noradrenergic signaling, stimulates axonogenesis through Trk receptors in pancreatic, ovarian, and colon cancers." (PMID 41030446, 2025). "We filtered four genes (BDNF, PTGS2, CTNNB1, and GSK3B) from the colon tumor and matched normal RNA-seq data, estimated the differences in fold change, and performed a t-test to determine the p value representing significant differences." (PMID 35054980, 2022). "In the present study, we showed that Caco-2, a human colonic cancer cell line, was responded significantly to stimulation of IBS-D FSN, followed by a significantly increased BDNF release." (PMID 25998025, 2015). "Colonic tumors express higher BDNF and TrkB transcriptomic and protein levels than non-neoplastic tissues." (PMID 30741921, 2019).
colon cancer (continued). "In addition, the activation of the BDNF/TrkB machinery in CRC cells and tissues and their critical roles in colon tumor growth have previously been demonstrated." (PMID 30741921, 2019). "Moreover, it has been shown that brain-derived neurotrophic factor (BDNF), a potent neurotrophic factor involved in cancer cell metastasis and migration, increases the migration of colon cancer cells by regulating VEGF/HO-1 pathway." (PMID 28475131, 2017). "BDNF was observed to be expressed in colon cancer tissues and normal tissues." (PMID 24255678, 2013).
panic disorder (23 papers, 2013 to 2025). An anxiety disorder characterized by multiple unexpected panic attacks with persistent concern of recurring attacks. "In conclusion, our systematic review and meta‐analysis demonstrate a significant association between lower BDNF levels and panic disorder." (PMID 38376041, 2024). "By aggregating data from multiple studies, we can increase statistical power, identify potential sources of heterogeneity, and explore subgroup analyses to uncover potential moderators or mediators of the BDNF‐panic disorder association." (PMID 38376041, 2024). "Despite these limitations, the consistent observation of lower BDNF levels among individuals with panic disorder provides important insights into the underlying neurobiology of this condition." (PMID 38376041, 2024). "The majority of studies included in our analysis were cross‐sectional in nature, limiting the ability to establish causality between BDNF levels and panic disorder." (PMID 38376041, 2024). "Several studies also examined the relationship between BDNF levels and panic disorder severity, suggesting a potential association between lower BDNF levels and more severe symptoms." (PMID 38376041, 2024). "Brain-derived neurotrophic factor (BDNF) is a candidate for susceptibility locus of Panic disorder (PD)." (PMID 35815047, 2022). "Therefore, more researches with high-quality design, large samples are needed to explore the association between BDNF Val66Met variant and panic disorder." (PMID 35815047, 2022). "Therefore, we aimed to compare BDNF protein levels between panic disorder patients and healthy controls to validate its biomarker potential and further elucidate the underlying pathophysiology of panic disorder." (PMID 38376041, 2024). "If BDNF alterations are consistently associated with panic disorder, it could potentially serve as a biomarker for diagnostic purposes, aiding in the identification and differentiation of individuals with panic disorder." (PMID 38376041, 2024). "The findings of our systematic review and meta‐analysis provide compelling evidence for lower BDNF levels among individuals with panic disorder." (PMID 38376041, 2024). "The pooled effect size indicated a statistically significant decrease in BDNF levels in individuals with panic disorder compared to healthy controls (SMD = −.53, 95% CI: −1.02 to −.04, p < .001; I2: 92%)." (PMID 38376041, 2024). "Recent studies reported lower BDNF protein levels in individuals with panic disorder compared to healthy controls." (PMID 38376041, 2024). "For example, individuals with panic disorder who had higher levels of BDNF in their blood serum showed a stronger average effect of exposure-based interventions than those with low BDNF concentrations." (PMID 37779399, 2024). "The findings suggest a potential role for BDNF dysregulation in the pathophysiology of panic disorders." (PMID 38376041, 2024). "Some studies have reported lower BDNF levels in individuals with panic disorder compared to healthy controls, suggesting a potential role for BDNF in the pathophysiology of the disorder." (PMID 38376041, 2024). "The investigation of BDNF in panic disorder is motivated by its critical role in the development and function of the central nervous system." (PMID 38376041, 2024). "The findings suggest a potential role for BDNF dysregulation in the pathophysiology of panic disorder." (PMID 38376041, 2024). "The qualitative synthesis revealed heterogeneity in terms of study design, BDNF measurement methods, and panic disorder severity measures." (PMID 38376041, 2024). "This systematic review and meta‐analysis provide evidence of lower BDNF protein levels in individuals diagnosed with panic disorder compared to healthy controls." (PMID 38376041, 2024). "Further research is warranted to elucidate the mechanisms through which BDNF is involved in panic disorder and to explore its potential as a therapeutic target for this debilitating condition." (PMID 38376041, 2024).
panic disorder (continued). "This systematic review and meta‐analysis provide evidence of lower BDNF protein levels in individuals diagnosed with panic disorders compared to healthy controls." (PMID 38376041, 2024). "It is important to note that the relationship between BDNF and panic disorder is complex and likely influenced by various factors." (PMID 38376041, 2024). "The meta‐analysis demonstrated a significant decrease in BDNF protein levels in individuals with panic disorder (SMD = −.53, 95% CI: −1.02 to −.04, p < .001; I2: 92%)." (PMID 38376041, 2024). "The role of BDNF in panic disorder can be understood within the context of its neurobiological functions." (PMID 38376041, 2024). "While in patients with panic disorder who had a poor response to cognitive behavioral therapy, significantly lower levels of serum BDNF were observed." (PMID 39408702, 2024). "The search strategy included relevant keywords and medical subject headings terms related to BDNF, panic disorder, and protein levels." (PMID 38376041, 2024). "This systematic review and meta‐analysis aim to synthesize the available evidence and determine the overall effect of BDNF protein levels in individuals diagnosed with panic disorder." (PMID 38376041, 2024). "Longitudinal studies are needed to determine the temporal relationship and potential bidirectional effects between BDNF alterations and panic disorder." (PMID 38376041, 2024). "Polymorphisms reducing BDNF expression have also been linked to increased incidence of panic disorder, and treatments for panic disorder increase BDNF expression." (PMID 38376041, 2024). "Plasma levels of BDNF are significantly lower in patients with panic disorder than in a control group." (PMID 36661490, 2022). "Patients with panic disorder had significantly reduced serum BDNF levels compared to controls before rest or exercise (p = 0.003)." (PMID 23908608, 2013). "Modulating BDNF levels or its downstream signaling pathways could represent a novel approach to the treatment and management of panic disorder." (PMID 38376041, 2024). "It highlights the potential involvement of BDNF dysregulation in the pathophysiology of panic disorder and suggests that targeting BDNF pathways may hold promise for the development of novel therapeutic interventions." (PMID 38376041, 2024). "The lower BDNF levels observed in panic disorder individuals may reflect dysregulation of the BDNF system, which could contribute to the development and maintenance of this disorder." (PMID 38376041, 2024). "A systematic review and meta‐analysis offers an opportunity to synthesize the existing evidence, overcome the limitations of individual studies, and provide a more comprehensive understanding of the relationship between BDNF protein levels and panic disorder, amending the conflicting literatures." (PMID 38376041, 2024). "The BDNF A/A genotype may diminish the plasma BDNF level and increase trait anxiety in panic disorder." (PMID 36661490, 2022). "Based on previous research, our objective was to test whether the BDNF Val66Met polymorphism and/or childhood maltreatment are associated with response trajectories during exposure-based CBT for panic disorder (PD)." (PMID 27355213, 2016). "Our aim was to study whether the BDNF Val66Met polymorphism and/or childhood maltreatment were associated with the outcome of exposure-based CBT for panic disorder (PD) in a naturalistic setting." (PMID 27355213, 2016). "Additionally, understanding the role of BDNF in panic disorder may open new avenues for targeted therapeutic interventions." (PMID 38376041, 2024). "BDNF Met/Met genotype may decrease plasma BDNF level and increase trait anxiety in panic disorder." (PMID 35815047, 2022). "A clinical study of panic disorder found that in patients receiving CBT, serum BDNF levels were significantly elevated in those who responded well." (PMID 39937424, 2025). "Therefore, this evidence strengthens the hypothesis that BDNF levels decrease in panic disorder." (PMID 38376041, 2024).
panic disorder (continued). "(2019) showed nonsignificant differences in serum BDNF levels between panic disorder patients and healthy controls." (PMID 38376041, 2024). "In particular, reduced serum levels of BDNF have been found in patients with panic disorders but no alterations were found for other ADs." (PMID 26539329, 2015). "In 672 adult subjects from six isolated villages in North-Eastern Italy with high inbreeding, we determined serum BDNF levels and identified subjects with different ADs subtypes such as Social and Specific Phobias (PHSOC, PHSP), Generalized Anxiety Disorder (GAD), and Panic Disorder (PAD)." (PMID 26539329, 2015).